TNFAIP3 (TNF alpha induced protein 3)
Diseases named in the same sentence as TNFAIP3 in open-access papers (continued):
Sharing a sentence is not in itself a finding about the gene and the disease.
rheumatoid arthritis (continued). "Genetic studies have demonstrated the association of TNFAIP3 single nucleotide polymorphisms (SNPs) with multiple human diseases, such as systemic lupus erythematosus (SLE), rheumatoid arthritis (RA), and Crohn’s disease (CD)." (PMID 29515565, 2018). "Accumulating evidences suggested that tumor necrosis factor alpha inducible protein 3 (TNFAIP3) gene rs10499194, rs13207033 polymorphisms may be associated with the risk of rheumatoid arthritis (RA)." (PMID 27779104, 2016). "Genes showing lower levels of expression in AD included ICAM-1, IL-1B, CCR1, IFIH1, SOCS1, TNFAIP3 and TNFSF13B, which are strongly associated with acute and chronic inflammation and adult rheumatoid arthritis." (PMID 26310571, 2015). "Several polymorphisms in or near the TNFAIP3 locus were described as being associated with inflammatory autoimmune pathology, including SLE, rheumatoid arthritis, multiple sclerosis and Type 1 diabetes." (PMID 26110642, 2015). "This study investigated five confirmed rheumatoid arthritis (RA) susceptibility genes/loci (HLA-DRB1, PTPN22, STAT4, OLIG3/TNFAIP3 and TRAF1/C5) for association with susceptibility and severity in an inception cohort." (PMID 20353580, 2010). "TNFAIP3, located at 6q23, has been identified as a susceptibility gene for both systemic lupus erythematosus (SLE) and rheumatoid arthritis (RA) in Caucasian and Asian populations." (PMID 20849588, 2010). "Among PSA T and NK cells, we also observed a downregulation of AP-1 transcription factors (JUN, JUNB, JUND, FOS) and regulators of activation (TNFAIP3, DUSP1) along with the upregulation of S100A11, a calcium-binding protein associated with rheumatoid arthritis." (PMID 35309349, 2022). "TNFAIP3,which is required for termination of the nuclear factor-κB (NF-κB) signal that is mediated by innate immune receptors, has been reported to be associated with SLE and rheumatoid arthritis." (PMID 23555688, 2013). "TNFAIP3 interacting protein 1, TNIP1 (ABIN-1) is involved in inhibition of nuclear factor-κB (NF-κB) activation by interacting with TNF alpha-induced protein 3, A20 (TNFAIP3), an established susceptibility gene to systemic lupus erythematosus (SLE) and rheumatoid arthritis (RA)." (PMID 20849588, 2010). "Single nucleotide polymorphisms (SNPs) in the TNFAIP3 locus have been associated to autoimmune disorders such as systemic lupus erythematous (SLE), rheumatoid arthritis (RA), psoriasis, type one diabetes, coeliac disease and multiple sclerosis (MS)." (PMID 32325694, 2020). "Recently, numerous researches have revealed that TNFAIP3 or TNIP1 gene polymorphisms were associated with susceptibility to some autoimmune inflammatory diseases including systemic lupus erythematous (SLE), systemic sclerosis (SSc), rheumatoid arthritis (RA) and psoriasis." (PMID 31308453, 2019). "For instance, TNFAIP3 has been identified to be related to the genetic etiology of systemic lupus erythematosus (SLE), rheumatoid arthritis (RA), systemic sclerosis (SSc)." (PMID 27556446, 2016).
autoimmune disease (68 papers, 2010 to 2025). A disorder resulting from loss of function or tissue destruction of an organ or multiple organs, arising from humoral or cellular immune responses of the individual to their own tissue constituents. "A20, or TNFAIP3, is a potent regulator of innate immune cell functions and is extensively linked to human inflammatory and autoimmune diseases." (PMID 41279106, 2025). "For instance, rs6920220 (G/A) has been linked to various autoimmune diseases, highlighting the importance of TNFAIP3 in immune regulation." (PMID 40771660, 2025). "Research has identified several SNPs within the TNFAIP3 gene that are associated with autoimmune diseases." (PMID 40771660, 2025). "Abnormal expression or mutation of TNFAIP3 is closely related to the pathogenesis of autoimmune diseases." (PMID 38573314, 2024). "Polymorphisms of TNFAIP3 in humans have been associated with autoimmune diseases and multiple cancers." (PMID 37965311, 2023). "The rs6920220 polymorphism in the TNFAIP3 gene is associated with the risk of many autoimmune diseases, including RA." (PMID 37893542, 2023). "TNFAIP3/A20 is a prominent autoimmune disease risk locus that is correlated with hypomorphic TNFAIP3 expression and exhibits complex chromatin architecture with over 30 predicted enhancers." (PMID 36199584, 2022). "TNFAIP3 was both highly upregulated in the T cells, which has been reported to be a common predisposing gene for autoimmune diseases, including VKH52." (PMID 35618758, 2022). "TNFAIP3 is a common autoimmune disease risk locus with several functionally characterized SNPs that regulate proinflammatory nuclear factor kB (NFκB) signaling implicated in the chronic inflammation and immune cell dysfunctions of autoimmunity." (PMID 35896530, 2022). "SNPs related to the TNFAIP3 gene had been well analyzed regarding the association with several autoimmune diseases including SLE." (PMID 33549127, 2021). "Polymorphisms within the tumor necrosis factor-α-induced protein 3 (TNFAIP3) genomic locus have been linked to multiple inflammatory and autoimmune diseases." (PMID 33680092, 2021). "As a test case, we investigated the TNFAIP3 locus because it has strong associations to many autoimmune diseases." (PMID 32144282, 2020). "In the present study, we investigated two TNFAIP3 gene SNPs in order to verify their possible association with the susceptibility to three different autoimmune diseases, specifically SLE, RA, and pSS, in Italian patients." (PMID 31534975, 2019). "Candidate gene studies and GWAS have reported associations of TNFAIP3 polymorphisms with several autoimmune diseases, including also SLE, RA, and pSS." (PMID 31534975, 2019). "Our results support the importance of the TNFAIP3 gene variant role in the development of different autoimmune diseases in the Italian population and furtherly confirm a sharing of genetic predisposing factors among these three pathologies." (PMID 31534975, 2019). "Its role in various innate and adaptive immune cells has been well established, and multiple SNPs in the vicinity of the TNFAIP3 gene have been associated with MS (e.g., rs17780048) as well as other autoimmune diseases." (PMID 30730892, 2019). "Regarding genetic background, TNFAIP3 SNPs have been associated with numerous inflammatory and autoimmune diseases." (PMID 30813592, 2019). "Genetic studies have suggested a role for TNFAIP3 in susceptibility to complex genetic autoimmune disorders (6, –, 12), including systemic lupus erythematosus (SLE) (13, –, 24)." (PMID 29343543, 2018). "TNFAIP3 is an essential negative regulator of inflammation, and dysregulation of TNFAIP3 is associated with autoimmune diseases." (PMID 30231487, 2018). "The “TT>A” allelic variant (tandem polymorphic dinucleotides rs148314165 and rs200820567; the risk allele is termed TT>A) located 41.6 kb downstream of the TNFAIP3 TSS is located within the most highly replicated ≈100 kb risk haplotype for autoimmune diseases." (PMID 29440643, 2018).
autoimmune disease (continued). "In summary, we demonstrated for the first time that autoimmune disease-associated risk variants (TT>A) in the TNFAIP3 gene play a protective role in brucellosis." (PMID 29343543, 2018). "The TT>A functional variants led to reduced expression levels of TNFAIP3 and enhanced NF-κB signaling, which predisposes individuals to autoimmune diseases while protecting them from brucellosis." (PMID 29343543, 2018). "Here we use BAC transgenics and genome editing to dissect, in vivo and in primary immune cells, enhancers that regulate human TNFAIP3, which encodes A20 and is linked with autoimmune diseases." (PMID 29440643, 2018). "Our humanized transgenic model provides a platform for dissecting tissue-specific enhancers and understanding regulation of TNFAIP3, and for identifying functionally important SNVs that are causally related with autoimmune diseases." (PMID 29440643, 2018). "TNFAIP3 is a critical negative regulator of pro-inflammatory nuclear factor kappa B (NF-κB) signaling implicated in many autoimmune diseases, and therefore a suspected target gene of the identified enhancer." (PMID 30268153, 2018). "Genome-wide association studies (GWASs) of various autoimmune diseases have reported significant associations with sequence variants in the vicinity of the TNFAIP3 gene." (PMID 29343543, 2018). "When it comes to TNFAIP3 rs10499194, there were several researches identified that it was significantly associated with the susceptibility of autoimmune diseases." (PMID 28702029, 2017). "Of note, polymorphisms of the TNIP1 gene, a molecule which interacts with the TNFAIP3 gene regulating the NF-κB activation, have been recently found to confer increased risk to SS and other autoimmune diseases." (PMID 26550578, 2015). "Several genetic variants of the TNFAIP3 gene have been associated with autoimmune diseases including SS." (PMID 26550578, 2015). "A20’s anti-inflammatory functions are important for human disease, as genome wide association studies (GWAS) have linked polymorphisms of the A20/TNFAIP3 gene to multiple inflammatory and autoimmune diseases including inflammatory bowel disease." (PMID 23671587, 2013). "The SLE associate TT>A risk alleles, through their inability to effectively deliver NF-κB to the TNFAIP3 promoter, impair A20 expression leading to enhanced NF-κB pathway activity and predisposition to autoimmune disease." (PMID 24039598, 2013). "Several genetic studies have suggested a role for TNFAIP3 in the susceptibility to complex autoimmune disorders." (PMID 23555688, 2013). "In humans, at least 8 GWAS in 5 autoimmune diseases have reported genome wide significant associations with variants in the vicinity of TNFAIP3 and others have reported suggestive association." (PMID 24039598, 2013). "Polymorphisms within the TNFAIP3 genomic locus, located at 6q23, have been associated with autoimmune disorders such as SLE in Caucasian, Asian and Japanese populations." (PMID 23227085, 2012). "Short of TNFAIP3 results in a number of diseases, such as TNFAIP3-deficient B cells prone to producing auto antibodies to contribute to autoimmune diseases." (PMID 23029332, 2012). "For example, the TNFAIP3 gene (encoding the A20 protein, a negative regulator of the NF-κB pathway) is located on chromosome 6q23, and variants in this gene are implicated in multiple autoimmune diseases including RA and IBD." (PMID 41425598, 2025). "The second hypothesis is supported by recent genetic studies, which have identified shared susceptibility loci, such as CTLA4, PTPN22, and TNFAIP3, across multiple autoimmune diseases." (PMID 40725836, 2025). "Indeed, Tnfaip3 a central immune regulator, is linked to increased susceptibility to many inflammatory and autoimmune diseases, and has recently been found to play a central protective role for the maintenance of CNS homeostasis." (PMID 35464428, 2022).
autoimmune disease (continued). "Variants in TNFAIP3 have been associated with multiple autoimmune diseases, susceptibility to allergy and asthma, and periodic fever syndromes, suggesting that this variant could potentially play a role in disease." (PMID 29682366, 2018). "Notably, SNPs mapping to the TNFAIP3 region have been shown to be associated with Ps and PsA, but map to a different risk haplotype, tagged by rs610604, distinct to other autoimmune diseases." (PMID 27799070, 2016). "Additionally a better understanding of how rs9494885 polymorphism in TNFAIP3 affects risk and protection in autoimmunity will provide valuable mechanistic insights into the pathogenesis and treatment of autoimmune disease." (PMID 23555688, 2013). "Furthermore, recent findings from GWA studies have revealed significant associations between variants in the human TNFAIP3 locus and a wide spectrum of autoimmune diseases." (PMID 23049601, 2012). "Thus, by altering immune activation thresholds human TNFAIP3 genetic variants may contribute to the fertility impairment observed in females with autoimmune disease." (PMID 35464428, 2022). "This variant is intergenic, located approximately 200 kb from TNFAIP3, and is associated with RA, coeliac disease (CeD), IBD and 8 other autoimmune diseases." (PMID 34508276, 2022). "The deficiency of TNFAIP3 in MSCs can induce immune thrombocytopenia and influence megakaryocytic differentiation through terminating the NF-κB pathway that suggests TNFAIP3 play a critical role in the process of MSCs alleviate s autoimmune disease." (PMID 32489333, 2020). "It blocks NF- kβ activation which mediates immune responses; thus, TNFAIP3 plays a key role in controlling inflammation in autoimmune diseases and is suggested as an attractive candidate for drug targeting." (PMID 32099610, 2019). "We wished to understand the regulation of human TNFAIP3 and identify functionally important enhancers that are relevant for autoimmune diseases in vivo." (PMID 29440643, 2018). "Cell-specific deletions of A20 resemble human autoimmune diseases, from a mild autoimmune phenotype in Tnfaip3 Cd19 (B-cell) KO mice to severe spontaneous inflammation in mice with A20-deficient dendritic cells." (PMID 28469620, 2017). "Nowadays the multiple potential roles of TNFAIP3 in regulating autoimmune diseases are not fully understood, and are likely to be cell and context dependent." (PMID 23555688, 2013). "Overall these studies highlight the important role that both TNFAIP3 and TNIP1 play in genetic predisposition to autoimmune disorders such as SLE." (PMID 23227085, 2012). "For example, a number of autoimmune diseases have been associated with variants in the PTPN22, TNFAIP3 and CTLA4 genes." (PMID 20854658, 2010). "TNFAIP3 encodes A20, a negative regulator of NF-κB-induced signalling, whereby the non-synonymous polymorphism rs2230926 in the A20 de-ubiquitinase (DUB) domain precipitates the development of autoimmune diseases including SLE." (PMID 37239388, 2023). "In summary, this study demonstrates that SNPs carried on the ∼109 kb SLE risk haplotype facilitate hypermorphic IL20RA and IFNGR1 expression, while suppressing TNFAIP3 expression, adding to the mechanistic potency of this critically important locus in autoimmune disease pathology." (PMID 36199584, 2022). "We found that TNFAIP3 serum level decrements are associated with the onset of a relapse in individual MOG-AAD patients and thus has significant potential as a biomarker and therapeutic target for MOG-AAD and other autoimmune diseases." (PMID 32709905, 2020). "Polymorphisms in four genes encoding proteins that control the MyD88-IRAK4-IRAK1 pathway have been reported to predispose to SLE and other autoimmune diseases in many human populations, namely, TLR7, IRAK1, TNIP1, and TNFAIP3." (PMID 31694920, 2019).
autoimmune disease (continued). "Naturally occurring functional variants (rs148314165 and rs200820567, collectively referred to as TT>A) reduce the expression of the tumor necrosis factor alpha-induced protein 3 (TNFAIP3) gene, a negative regulator of NF-κB signaling, and predispose individuals to autoimmune disease." (PMID 29343543, 2018). "This indicates that TNFAIP3 SNP analysis before TNF-blocking therapy initiation is worthwhile to perform in several autoimmune diseases and may be more practical than evaluating TNFAIP3 mRNA expression." (PMID 29515565, 2018). "Considering the association of TNFAIP3 SNPs with the RA and SLE as well as other autoimmune diseases, it is believed that the genetic variations of the TNFAIP3 gene may play an important role in the susceptibility of LOMG." (PMID 28514294, 2017). "TNFAIP3-deleted mice with constitutive NF-κB activation demonstrate the overproduction of pro-inflammatory cytokines, severe multi-organ inflammation, enhanced proliferation upon activation, and finally develop autoimmune disease." (PMID 28152507, 2017). "TNFAIP3 is widely considered as an important regulator of inflammation and immunity, and plays a key role in the modulation of immune response to pathogens as well as the development of inflammatory and autoimmune disease." (PMID 27919278, 2016). "We intend to examine the genetic contribution of TNFAIP3, IFIH1, and IRF5 to PM/DM based upon the postulated roles of each of these genes' products in innate and cell-mediated immunity in PM/DM and their described associations with autoimmune diseases." (PMID 25337792, 2014). "TNFα-induced protein 3(TNFAIP3) is a key regulator of inflammation and immunityinvolved in the development of various autoimmune diseases and it also desensitizescells from TNFα-induced cytotoxicity and was shown to be anti-apoptotic inbreast cancer MCF7S1 cells." (PMID 21637860, 2011). "Data from the current study extend that of previous work identifying that CTLA-4, the IL2_21 region, 6q23 (TNFAIP3), SH2B3, PRKCQ, MMEL1 and now TAGAP are susceptibility loci that are common to the three autoimmune diseases examined in the current study: T1D, CeD and RA." (PMID 20854658, 2010). "Indeed, although there are several studies on TNFAIP3 and even meta-analysis regarding the association of this gene in many diseases, it has not been investigated in the Italian patients with autoimmune diseases." (PMID 31534975, 2019). "Finally, we discuss the latest findings on TNFAIP3 SNPs in human autoinflammatory and autoimmune diseases and address that genotyping of TNFAIP3 SNPs may guide treatment decisions." (PMID 29515565, 2018). "Notably, our study found that the top single nucleotide polymorphism (SNP) associated with SS located in TNFAIP3 was rs5029939, which is similar to previous findings that this SNP has been associated with various autoimmune diseases, including SLE, systemic sclerosis, and other autoimmune disorders." (PMID 38933282, 2024). "Indeed, mice harboring targeted cell-specific deletions in the TNFAIP3 gene in innate immune cells develop autoinflammatory diseases spontaneously, and mice harboring targeted cell-specific deletions in adaptive immune cells develop spontaneous inflammation that resembles human autoimmune diseases." (PMID 38183052, 2024). "Top SNPs shared between RA and CD, as well as RA and UC or UC and CD, lie in regions well-known to be shared across multiple autoimmune diseases, such as the HLA, IL23R, TNFAIP3, and IL2RA." (PMID 29309429, 2018). "It was found that these cells, which differentially express another key RA gene, TNFAIP3, could differentiate into cytotoxic CD4+ T cells, potentially contributing to the pathogenesis of autoimmune diseases." (PMID 39930543, 2025).